IL6 (interleukin 6)
Diseases named in the same sentence as IL6 in open-access papers (continued):
Sharing a sentence is not in itself a finding about the gene and the disease.
meningococcal infection (9 papers, 2012 to 2025). Infections with bacteria of the species neisseria meningitidis. "A cohort of 448 isolates from patients with invasive meningococcal disease in the Netherlands were screened for the ability to induce IL-6 in monocytic cell Mono Mac 6 cells." (PMID 23209568, 2012). "The soluble cytokines investigated here included the instructive cytokines IL-6 and TNF, which are often described in the context of meningococcal infections and exposures." (PMID 38443838, 2024). "Among these, the pro-inflammatory cytokines IL-6, which stimulates acute phase responses, haematopoiesis, and immune reactions, and TNF-α, a central early immune response activator, have both been related to meningococcal disease severity." (PMID 40818988, 2025). "Although to our knowledge a role of IκBζ during meningococcal infection has not been reported up to now, IκBζ-induced expression of IL6 was described for human lung epithelial cells after treatment with the Gram-negative bacterium Legionella pneumophila." (PMID 25347003, 2014). "In total 467 cases of invasive meningococcal disease were reported to NRLBM, and of 448 cases (96%) both clinical data and in vitro IL-6 induction could be studied." (PMID 23209568, 2012).
ocular toxoplasmosis (9 papers, 2011 to 2024). Ocular toxoplasmosis is an infection in the eye caused by the parasite, Toxoplasm a gondii. "IL‐6 polymorphism and ocular toxoplasmosis are significantly correlated, according to Cordeiro's study." (PMID 38270309, 2024). "This study found that a reduction in IFN-γ and an increase in IL-6 and IL-10 production was associated with protection against vertical transmission and ocular toxoplasmosis in the offspring." (PMID 33658997, 2020). "Interleukin-6 (IL-6), a pro-inflammatory cytokine associated with pathogenesis of AMD, as well as in a model of ocular toxoplasmosis, and has been shown in vitro to be regulated by IL-1β, following IL-1β-dependent activation of the p38 MAPK/NF-kB pathway." (PMID 31379825, 2019). "On the other hand, another study reported a substantial role for IL-6 in the retinal inflammatory response in a mouse ocular toxoplasmosis reactivation model." (PMID 30386320, 2018). "Additionally, a deleterious role of Il6 has been characterised in experimental ocular toxoplasmosis via antibody neutralisation, which considerably improved retinal morphology compared to controls." (PMID 26911327, 2016).
Paget disease (9 papers, 2011 to 2024). A malignant neoplasm composed of large cells with large nuclei, prominent nucleoli, and abundant pale cytoplasm (Paget cells). "Limitations of the IL-6 diagnostic method in serum are the reportedly elevated IL-6 levels in patients with chronic inflammatory diseases, Paget disease and immunodeficiency syndromes." (PMID 24586496, 2014). "Paget’s disease patients have elevated IL-6 in marrow plasma and peripheral blood, and their osteoclasts express high IL-6." (PMID 38457001, 2024). "Increased sIL-6R levels have been found in the sera of Paget disease patients with LBP, suggesting an enhanced transmission of IL-6 signaling in the specialized neural system linked to irregular perception in these patients." (PMID 35909446, 2022). "Several theories have proposed that IL-6 is a critical inducer in the development of pagetic osteoclasts and bone lesions in Paget's disease induced by MV." (PMID 29312244, 2017). "Additionally, interleukin 6 (IL6) is a major pro-inflammatory cytokine that stimulates the formation and activity of bone-resorbing osteoclasts in vitro, playing a key role in bone disorders such as Paget ́s disease." (PMID 38449853, 2024). "Immunohistochemical studies of bones from Paget’s disease patients showed that pagetic osteoclasts contained abundant platelet-derived growth factor, transforming growth factor-β and IGF1, as well as IL-6." (PMID 38457001, 2024). "In addition, IL-6 may also make preosteoclasts more sensitive to RANKL stimulation, presumably due to an IL-6-mediated upregulation of RANK receptors, which was previously shown in Paget's disease." (PMID 30671025, 2018). "However, transgenic overexpression of IL-6 in osteoclasts did not induce a pagetic phenotype in osteoclasts or pagetic lesions in mice, suggesting that other factors induced by MVNP are needed for the development of Paget’s disease." (PMID 38457001, 2024).
pituitary tumor (9 papers, 2017 to 2025). A benign or malignant neoplasm affecting the pituitary gland. "Moreover, by studying the secretome of tumor-associated fibroblasts derived from pituitary tumors, the authors found, for example, that the fibroblasts derived from invasive pituitary tumors were secreting higher levels of IL6 compared to the fibroblasts derived from non-invasive pituitary tumors." (PMID 31640258, 2019). "The results of the analysis indicated significantly lower levels of DHEA-S (p = 0.007) and albumin (p < 0.001), and higher levels of IL-6 (p < 0.001) in patients with pituitary tumours, relative to the healthy controls." (PMID 41234225, 2025). "In patients with pituitary tumours, we also found higher levels of IL-6 and lower levels of albumin." (PMID 41234225, 2025). "Regarding pituitary tumors, IL6 promotes cell growth by paracrine means, whereas by autocrine means, it promotes senescence and prevents malignant transformation." (PMID 37958474, 2023). "In pituitary tumours, it has been shown that IL-6 was mainly produced by tumour cells, and that its silencing in primary cultures of human pituitary tumours decreased tumour senescence." (PMID 35139928, 2022). "We found that IL-6 expression was downregulated 17.1-fold in human pituitary tumor tissue compared to normal pituitary tissue." (PMID 35600354, 2022). "Taking into account that IL-6 participates in the progression of pituitary tumors, and its role in OIS, this cytokine appears as a candidate for an autocrine/paracrine regulator of pituitary adenoma control." (PMID 27902467, 2017). "Moreover, the IL-6/JAK2/STAT3 pathway seems to be involved in the invasiveness of pituitary tumors by increasing the expression of MMP-9." (PMID 37958702, 2023). "In particular, it is known that IL-6 participates in pituitary tumor development and progression." (PMID 27902467, 2017). "IL-6 is involved in pituitary tumor progression and is produced by the tumoral cells." (PMID 27902467, 2017). "Here we prove that autocrine IL-6 participates in pituitary tumor senescence." (PMID 27902467, 2017). "The present feedback is in accordance with the Lauritano et al29 trial that determined a strong positive correlation between the basal production of IL-6, IL-1, and VEGF in human pituitary tumors." (PMID 41332947, 2025). "The first group was associated with kinine response and produced interleukin-6, which is involved in promoting mitogenic growth and pituitary tumorigenesis, suggesting a possible role of inositols in the control of mechanisms involved in the cell growth of some, but not all, pituitary tumors." (PMID 39199391, 2024).
primary immunodeficiency (9 papers, 2019 to 2026). "IL-6 participates in host defense immune reactions against viral, parasitic, fungal and bacterial infections and primary immunodeficiency diseases involving IL-6 or its signaling pathways confirm these observations." (PMID 35154093, 2022). "Through correlation analysis, we found that SAA2 might be involved in classic signals involving in cancer progression, including cytokine and receptor interaction, primary immunodeficiency, drug metabolism, IL6-JAK-STAT3, E2F, and the G2M checkpoint." (PMID 39457484, 2024). "Interestingly, many immune-related pathways were also enriched, including primary immunodeficiency, IL6-JAK-STAT3 signaling and the IL2-STAT5 pathway." (PMID 36226186, 2022). "Targeting IL-6 signaling could, therefore, represent a potential therapeutic strategy to modulate antibody responses.IMPORTANCEThe difficult-to-treat MABS infection is a major clinical problem in Asian patients with adult-onset primary immunodeficiency associated with anti-IFN-γ autoantibodies." (PMID 42003588, 2026).
Respiratory insufficiency (9 papers, 2020 to 2025). "A correlation between IL-6 level and respiratory function has been described in a previous study in which higher IL-6 levels were associated with impeding respiratory insufficiency." (PMID 33281700, 2020). "First, transfusion of allogeneic blood products activatessystemic inflammatory responses and releases pro-inflammatory cytokines (e.g.,interleukin 6, tumor necrosis factor-α), leading to pulmonary capillaryleakage and alveolar edema, which in turn exacerbates respiratory insufficiency." (PMID 40630459, 2025). "Patients with severe respiratory impairment (P/F ratio less than 200) who were older than patients with P/F ratio >200 showed a lower number of lymphocytes in the venous blood, and the levels of d‐dimer and IL‐6 were significantly higher than in those with less‐severe disease." (PMID 34533859, 2022).
Right ventricular hypertrophy (9 papers, 2009 to 2024). In this case the right ventricle is more muscular than normal, causing a characteristic boot-shaped (coeur-en-sabot) appearance as seen on anterior- posterior chest x-rays. "We found that PH and right ventricular hypertrophy were less severe in IL-6-/- mice than in wild-type mice after 2 weeks of hypoxia." (PMID 19173740, 2009). "However, after 2 weeks hypoxia, RVSP was significantly lower and right ventricular hypertrophy less severe in IL-6-/- than in IL-6+/+ mice (P < 0.01)." (PMID 19173740, 2009). "Sevoflurane and thymoquinone can reduce IL-6 and TNF-α by inhibiting the NF-κB and MAPK pathways, partially inhibiting pulmonary vascular remodeling and right ventricular hypertrophy in PH rats." (PMID 37449201, 2023). "Hypoxia leads to upregulation of miR-27b in HPAECs, inhibits the expression of PPARγ and induces the secretion of IL-6, while fibroblast growth factor 21 (FGF21) can reduce the expression of IL-6 by inhibiting miR-27b, thus alleviating PH and right ventricular hypertrophy (RVH)." (PMID 37449201, 2023).
Rotavirus infection (9 papers, 2018 to 2024). Infection with any of the rotaviruses. "In an earlier study, RIB (the IMPDH2 inhibitor) decreased the IL-6/IL-8 secretion in the animal models of rotavirus infection." (PMID 36177032, 2022). "L. acidophilus increased the IL-6 response to rotavirus infection, which is consistent with the immunostimulatory effect of L. acidophilus on B- and T-cell immune responses; while L. rhamnosus significantly decreased IL-6 production by the IPEC-J2 cells." (PMID 31482249, 2019). "Rotavirus infection triggers the production of IL-8, IL-6, and TNF-α in IECs by activating the TLR3 and RIG-I pathways." (PMID 32038538, 2019). "The RV infection produced significant increases in both pro-inflammatory/Th1 (IL-12, IL-6) and anti-inflammatory/Th2 (IL-10) cytokines at the peak of infection, as found in several rotavirus infection models." (PMID 30406046, 2018). "Rotavirus infection also enhanced the expression of IL-6, IL-8, and MCP-1 in PIE cells." (PMID 34163470, 2021). "Following rotavirus infection, LGG therapy reduced the IL-6 response, indicating LGG’s anti-inflammatory properties in an IPEC-J2 cell line." (PMID 35208843, 2022). "Treatment with L. acidophilus (LA) before rotavirus infection boosted PRV replication and IL-6 response to PRV infection, indicating that LA had an adjuvant effect." (PMID 35208843, 2022). "When the inflammatory cytokines and chemokines were analyzed, it was observed that each treatment induced a characteristic change in IL-6, IL-8, and MCP-1 expression in PIE cells after rotavirus infection." (PMID 30319634, 2018).
schwannoma (9 papers, 2019 to 2026). A benign, usually encapsulated slow growing tumor composed of Schwann cells. "We identified epidermal growth factor receptor (EGFR) signaling as a key driver of schwannoma growth and an escape mechanism from anti-IL6 treatment." (PMID 41758723, 2026). "Their analysis confirmed previous findings since CM from painful schwannoma cell lines contained elevated levels of specific inflammatory cytokines (IL-6, IL-8, VEGF), compared with CM collected from cell lines derived from non-painful schwannomas." (PMID 40794298, 2025). "Previous studies revealed that lipopolysaccharides (LPS) treatment of the schwannoma in vitro improved the level of NFκB, IL-1β, pSTAT3, and IL-6 cytokines to activate an immune reaction." (PMID 31026579, 2019). "MMP-9 cleaves N-cad to drive schwannoma proliferation through IL-6/STAT3 and NF-κB signaling." (PMID 41756440, 2026). "While IL-1beta and IL-6 are increased in schwannoma and may contribute to tumor growth, especially IL-12 exerts a robust antitumor response." (PMID 33530441, 2021).
scleritis (9 papers, 2017 to 2024). Inflammation of the sclera. "On the other hand, we found that IL6 plays an important role in scleritis." (PMID 37063831, 2023). "TNF and IL6 are considered key mediators and possible drug targets of scleritis." (PMID 37063831, 2023). "The fact that marked infiltration of macrophages into the sclera was seen in our mouse model of scleritis suggests that TNF and IL-6, as cytokines produced by macrophages for innate immunity, represent appropriate target molecules." (PMID 35008766, 2021). "Monoclonal antibodies against TNF-α (all except Etanercept), IL-1 inhibitors (Anakinra), IL-6 inhibitors (Tocilizumab), and anti-CD20 (Rituximab) targeted-drugs have been shown to control inflammation and reduce scleritis flares, allowing for a corticosteroid-sparing effect." (PMID 38060142, 2023). "These cytokines target macrophages, and from the results of analysis of the CIA scleritis model in this study, it is possible that inhibition of IL1, IL-6, and TNF might also be effective in suppressing scleritis." (PMID 35008766, 2021). "Eighty-eight potential drugs were considered as candidates for the key genes TNF and IL6, and DALIMUMAB, ETANERCEPT, INFLIXIMAB, PF-04236921, and INSULIN were found to act against both TNF and IL6 and were identified as potentially contributing to the treatment of scleritis." (PMID 37063831, 2023). "Although various reports have described the use of molecularly targeted therapies using biologics such as TNF inhibitors, IL-6 inhibitors, CTLA4Ig, anti-CD20 antibody, and anti-CD25 antibody, the optimal molecules to target with molecularly targeted therapy in scleritis have remained unknown." (PMID 35008766, 2021). "It was found that TNF was the highest-scoring hub gene in all scleritis subtypes, TNF and IL6 and their targeted drugs remained applicable to non-infectious scleritis and anterior scleritis." (PMID 37063831, 2023).
scoliosis (9 papers, 2012 to 2025). A congenital or acquired spinal deformity characterized by lateral curvature of the spine. "Therefore, we hypothesized that basophils might exert a risk role through IL-6 in the context of scoliosis." (PMID 40177401, 2025). "In conclusion, the homozygous GG genotype of IL-6 was associated with a higher risk of scoliosis (GG versus CC, OR: 3.5; 95% CI: 1.54–7.98) and the presence of the G allele (G versus C, OR: 2.02; 95% CI: 1.35–3.03) could be considered as susceptibility factor to IS." (PMID 26199858, 2015). "Higher level of IL-6 expression was found in herniated discs from patients with chronic sciatic pain than in patients with painless scoliosis." (PMID 32541845, 2020). "Other authors have evaluated the possibility that gene variants of IL-6 and MMPs might be associated with scoliosis and suggest that MMP-3 and IL-6 promoter polymorphisms constitute important factors for the genetic predisposition to scoliosis." (PMID 29435499, 2018). "Other authors have evaluated the possibility that gene variants of IL-6 and MMPs might be associated with scoliosis and suggests that MMP-3 and IL-6 promoter polymorphisms constitute important factors for the genetic predisposition to scoliosis." (PMID 22264320, 2012). "The presence of scoliosis was significantly associated with IL-4 (r = 0.424, P < 0.0001), IFN-γ (r = −0.458, P < 0.0001), IL-12p70 (r = −0.327, P = 0.0029), IL-4/IFN-γ ratio (r = 0.491, P < 0.0001), IL-5/IFN-γ ratio (r = 0.442, P = 0.0001), and IL-6/IFN-γ ratio (r = 0.429, P = 0.0001)." (PMID 26236424, 2015). "Of relevance to developmental PCP signaling, at the onset of scoliosis in zebrafish lacking the vertebrate-specific PCP component Protein tyrosine kinase 7 (Ptk7), TNF is highly expressed and triggers Il-6 expression." (PMID 37589075, 2023).
septic peritonitis (9 papers, 2016 to 2025). Septic peritonitis is an inflammatory condition of the peritoneum that occurs secondary to microbial contamination. "Hence, the diminished IL-6 concentration in the peritoneal cavity and in serum through BaP exposure may indicate a reduced severity of septic peritonitis in our model." (PMID 35203386, 2022). "Mice challenged with septic peritonitis had significantly higher plasma levels of TNF-α, IL-6, IL-10, and IFN-γ compared to the sham-operated mice." (PMID 34366711, 2021). "To get insight into the influence of gzmA and gzmB deficiency on the local inflammatory response elicited during septic peritonitis, we measured proinflammatory (TNF-α, IFN-γ, and IL-1β, IL-6) and anti-inflammatory (IL-10) cytokines as well as MCP-1 and KC levels in PLF." (PMID 28694562, 2017). "In dogs with septic peritonitis, levels of the inflammatory cytokines C-C motif chemokine ligand 2 (CCL2) and interleukin 6 (IL-6) were significantly higher than in non-septic dogs, which contributes to migration and infiltration of macrophages into the area of insult." (PMID 33778035, 2021).
T-cell lymphoma (9 papers, 2014 to 2024). "B and T cell lymphomas have a different serum cytokine signature, with T cell lymphoma associated with increased levels of IL-6, whilst IL-10 is more prominent in B cell lymphoma–affected canine patients." (PMID 30987001, 2019). "Of the 6 Δ122/Δ122 IL-6+/− mice with T-cell lymphoma, 4 had extensive spread, and of the 9 Δ122/Δ122 IL-6−/− mice with a T-cell lymphoma, 5 showed local spread and 4 mice had extensive spread." (PMID 29343721, 2018). "Eighty-nine percent of the T-cell lymphomas from Δ122/Δ122 IL-6+/+ showed extensive spread to the liver, spleen, salivary gland, kidney and nodes." (PMID 29343721, 2018). "The CSF IL-10 level mildly increased, but the IL-10/IL-6 ratio was 0.16 (<0.72), in one case of T-cell lymphoma involving the leptomeninges." (PMID 27924864, 2016). "For example, B-cell lymphoma may exhibit higher levels of IL-10 and TK1 than T-cell lymphoma, while T-cell lymphoma may show higher levels of IL-6." (PMID 39682357, 2024). "Using cytokine array analyses, we found that IL-6 was increased in PI3K inhibitor-resistant B- and T-cell lymphoma cells, and showed that the acquired resistance to copanlisib and duvelisib reflected two mechanisms in common: upregulation of IL-6 and activation of STAT3/5." (PMID 31601188, 2019). "In Δ122/+ IL-6+/− mice, 3/6 mice had T-cell lymphomas of which 2 displayed extensive spread." (PMID 29343721, 2018). "Of the Δ122/+ IL-6−/− mice, only 1 mouse had a T-cell lymphoma that showed limited spread." (PMID 29343721, 2018). "In summary, the loss of IL-6 in ∆122/∆122 mice resulted in decreased levels of serum cytokines and chemokines involved in the JAK-STAT pathway and significantly decreased the incidence of T-cell lymphomas with extensive spread." (PMID 29343721, 2018). "In T-cell lymphoma cells, TGM2 up-regulates the IL-6/JAK/STAT3 pathway, which proliferates the growth of T-cell lymphoma cells." (PMID 39115570, 2024). "On the basis of these findings, we speculate that activation of IL-6 signaling may contribute to the PI3K resistance of B- and T-cell lymphoma cells." (PMID 31601188, 2019).